CD4 (CD4 molecule)
Diseases named in the same sentence as CD4 in open-access papers (continued):
Sharing a sentence is not in itself a finding about the gene and the disease.
Chagas disease (continued). "We applied unsupervised clustering using a self-organizing maps algorithm (FlowSOM - FS) to further explore distinct CD4+ T cell phenotypes among patients with different clinical forms of Chagas disease." (PMID 38726014, 2024). "As the immune system relies on CD4+ T helper 1 (Th1) cells for protective immunity during the acute and chronic stages of Chagas disease, it is reasonable to expect higher parasitaemia and poor disease control in immunocompromised patients." (PMID 37987164, 2024). "In previous studies, the lymphocytic infiltrate in the chronic phase of Chagas disease was described as being composed of CD4+ and CD8+ T lymphocytes." (PMID 37764892, 2023). "The increased frequency of CD69+CD4+ T cells suggests a constant activation by remaining parasites or antigens that persist into the Chagas disease’s chronic phase." (PMID 36447264, 2022). "Taken together, these data indicate a higher expression of CD69 in CD4+ T cells in patients with Chagas disease, especially in those in the indeterminate form (A) and established chronic cardiomyopathy (B2-C-D)." (PMID 36447264, 2022). "Unsupervised clustering revealed an increase of CD69+ cells among TN (MC1) and memory (MC4 and MC5) CD4+ T cells in PBMC from patients with Chagas disease." (PMID 36447264, 2022). "Trypanosoma cruzi-specific IFN-γ+CD4+ T cells are increased in CCC patients after antigenic recall when compared to patients in the indeterminate form of Chagas disease." (PMID 36447264, 2022). "Here, we used high dimensional flow cytometry to phenotype CD4+ T cells from patients in different stages of chronic Chagas disease compared to healthy individuals." (PMID 36447264, 2022). "To investigate the CD4+ T cell compartment during chronic chagasic infection, we analyzed peripheral blood from patients displaying different forms of Chagas disease using high-dimensional flow cytometry." (PMID 36447264, 2022). "In children and newborns, the TCR repertoire was similar to the one found in acute and chronic phase of Chagas disease in adults, which was mainly characterized by a decrease of frequency Vβ5 CD4+ T cells." (PMID 36107855, 2022). "In our study, a consistent increase in the frequencies of CD69+CD4+ T cells among all T cell subsets was observed during Chagas disease." (PMID 36447264, 2022). "Cytotoxic CD4+ T cells co-expressing granzyme B and perforin were expanded in patients with Chagas disease and were higher in patients with mild CCC compared to controls." (PMID 36447264, 2022). "To understand the mechanisms by which plasmablasts regulate the CD4+ T cell response in experimental Chagas disease, we first investigated the kinetics of the plasmablast response." (PMID 35651611, 2022). "Our previous studies in human Chagas disease have shown that the frequency of Vβ5+ CD4+ T cells is decreased in acute infection and increased in the peripheral blood of chronic Chagas patients." (PMID 36107855, 2022). "We confirmed the reduced frequencies of CD39+ TREG among CD4+ T cells during Chagas disease compared to controls by manual gating analysis." (PMID 36447264, 2022). "We used high dimensional flow cytometry to assess the heterogeneity of CD4+ T cells from patients in various stages of Chagas disease." (PMID 36447264, 2022). "The increased frequencies of cytotoxic CD4+ T cells in patients with Chagas disease suggests a role of these cells in the pathogenesis of cardiomyopathy." (PMID 36447264, 2022). "Reports in the literature have demonstrated the relationship between the reactivation of the Chagas disease with a decrease in CD4 T-cells and increase in VL." (PMID 35353834, 2022). "In the present study, we found that the frequency of parasite-specific CD4+PRF+ T cells is increased in the circulation of chronic cardiac patients with Chagas disease (CC) when compared to HD." (PMID 35670567, 2022).
Chagas disease (continued). "The CD4+ and CD8+ T cell immune response against T. cruzi, the parasite causing Chagas disease, are relevant for both parasite control and disease pathogenesis." (PMID 34267750, 2021). "And more recently, another predictive approach developed by our group led to the discovery of peptides demonstrated to induce CD4+ T cell response in Chagas disease patients." (PMID 34267750, 2021). "The functional capacity of CD4+ T cells was analyzed by cytometric assays in chronic Chagas disease patients, with indeterminate form (IND) and cardiac alterations (CCC) (25 and 15, respectively) before and after benznidazole treatment." (PMID 33539379, 2021). "Distribution of patients according to category of CD4+ cells/μL and site of Chagas disease reactivation." (PMID 34591866, 2021). "Our results that DN T cells of the CM phenotype are predominant and associated with a more balanced immune response in IND agree with studies evaluating the memory response of CD4+ T cells in human Chagas disease." (PMID 34868005, 2021). "The frequency of CD4+CD8+ T cells was higher in chronic Chagas disease patients compared with healthy donors." (PMID 29750791, 2018). "Elevated expression of TIM-3 by CD4+CD8+ T cells from symptomatic compared with asymptomatic Chagas disease patients has been observed." (PMID 29750791, 2018). "As seen in animal models of Chagas disease, there is a strong thymic atrophy due to massive death of CD4+CD8+ double-positive cells by apoptosis and an abnormal escape of immature and potentially autoreactive thymocytes from the organ." (PMID 29963015, 2018). "It has been reported that the CD4+CD8+ T cell population expands in chronic Chagas disease patients." (PMID 29750791, 2018). "Seeking to contribute to the scarce existing knowledge on the specificity of memory CD4+ T cells in Chagas disease, we decided to focus our efforts on this population." (PMID 28552984, 2017). "Our results therefore indicate that GRAIL is an important player in CD4 T cell anergy during the acute phase of Trypanosoma cruzi infection." (PMID 28114324, 2017). "In Chagas disease, Trypanosoma cruzi-infected children, at early stages of infection, displayed mainly double- or triple-functional CD4+ T-cells whereas chronically infected adults showed monofunctional T-cell specific-responses." (PMID 26575186, 2015). "Regarding TH17 cells in Chagas disease, a recent study showed a lower frequency of circulating CD4+IL-17+ T cells in CCC patients as compared with ASY patients and noninfected individuals." (PMID 25152568, 2014). "The goal of this study was to evaluate the role of antigen-specific induced CD4+CD25+ T cells during Chagas disease, either controlling or exacerbating infection by T. cruzi." (PMID 23509755, 2013). "Results show that indeed rSSP4 induced expansion of CD4+CD25+FOXP3+ T cells that exacerbate Chagas disease by promoting parasite proliferation during acute T. cruzi infection." (PMID 23509755, 2013). "All groups of Chagas' disease patients presented the same frequency of CD4+CD25+ regulatory T cells." (PMID 22545173, 2012). "As we suspected, CD4+CD25+ T cells from Chagas' disease patients with severe cardiomyopathy presented reduced capacity to suppress T cell proliferation when compared to free/mild cardiomyopathy patients and healthy individuals." (PMID 22545173, 2012). "The frequency of CD4+CD25+ regulatory T cells among patients with different clinical forms of Chagas disease was also examined in the present study." (PMID 22545173, 2012). "This is not in agreement with a previous report showing lower values of CD4+CD25high T cells among school children with the indeterminate form of Chagas disease than that values observed in healthy children." (PMID 22545173, 2012).
Chagas disease (continued). "Our results are in agreement with these findings and we suggest that in Chagas' disease CD25High CD4+ T cells can migrate to the tissues and control the severe inflammatory response in individuals with the IND clinical form of the disease." (PMID 21655351, 2011). "More recently, we have evaluated the potential role of CD25High CD4+ T cells in the control of Chagas' disease pathogenesis." (PMID 21655351, 2011). "Similar results have been demonstrated by other study, in which patients in the chronic phase of Chagas disease presented the same expression profile of CD45RAlow in both CD4+ and CD8+ peripheral T cells." (PMID 19742301, 2009). "In this respect, it is noteworthy that CD4+ T cell-mediated autoreactivity against myocardial cells has been experimentally demonstrated in murine Chagas disease." (PMID 16846255, 2006). "Taken together, the stratification of Eff CD4+ T cells may represent a new marker of the clinical progression of Chagas disease." (PMID 38726014, 2024). "Our findings show that Chagas disease alters circulating CD4+ T cell compartments." (PMID 38726014, 2024). "Therefore, a comprehensive analysis of CD4+ T cell and B cell subsets across distinct clinical forms of Chagas disease is crucial." (PMID 38726014, 2024). "In addition, we evaluated the main cytokines produced by total CD4+ T cells after anti-CD80 or anti-CD86 antibody blockade from PBMC cultures of Chagas disease patients and healthy individuals." (PMID 35665256, 2022). "In this sense, either antigenic stimulation or chronic release of pro-inflammatory cytokines could induce and sustain an activated status among CD4+ T cells in patients with Chagas disease." (PMID 36447264, 2022). "Here, GrB+PFN+CD4+ T cells were expanded in patients with Chagas disease compared to controls." (PMID 36447264, 2022). "Previous reports have shown an expansion of cytotoxic CD4+ T cells during Chagas disease." (PMID 36447264, 2022). "This study evaluates the laboratory parameters related to Chagas disease parasite load, such as qPCR and blood culture, and assesses the PLHIV immune markers of CD4 T-cells and viral load to verify the possibility of Chagas disease reactivation in co-infected individuals." (PMID 35353834, 2022). "Baseline levels of NK, NKT, and CD4+ CD25high cells, increased expression of activated CD8+ T cells associated with failed immunoregulation mechanisms were associated with cardiac symptoms of chronic Chagas disease." (PMID 34489964, 2021). "Furthermore, we found an increased proportion of CD4+granzyme-perforin+ T cells in CCC versus IND Chagas disease patients and that CCC had a CD4+granzyme B+INF-γ+ T cell population, which was absent in IND." (PMID 33539379, 2021). "Furthermore, the highest impact of benznidazole treatment observed in our study was related to the expression levels of the PD-1 marker by CD4+ T cells, which markedly declined after treatment in indeterminate and cardiac Chagas disease patients." (PMID 33539379, 2021). "Despite having CD4 counts greater than 200, T. cruzi DNA can still be detected in the blood of those infected with HIV, which likely indicates those living with HIV are at continued risk for reactivation Chagas disease." (PMID 34821818, 2021). "The immune response mediated by CD4+ T lymphocytes is highly important for the development of Chagas disease involving the Th1, Th2, Th17, or Treg CD4+ lymphocytes that differ in their functions, secreted cytokine pattern, and specific expression of transcription factors." (PMID 29599775, 2018). "In summary, these findings suggest that CD4+CD8+ T cells could be an important component of the immune response against T. cruzi infection during the chronic phase of Chagas disease." (PMID 29750791, 2018). "CD4+CD8+ T cells form a poorly studied population of T cells in the context of Chagas disease." (PMID 29750791, 2018).
Chagas disease (continued). "Furthermore, the observed pattern of the frequency of CD4+CD8+ T cells from Chagas disease patients, expressing some inhibitory receptor is similar to that reported by the CD8+ T cells." (PMID 29750791, 2018). "Thus, the aim of this work was to search for a novel link between GRAIL and CD4 T cell unresponsiveness in the context of abnormalities of T cell proliferation observed during Trypanosoma cruzi infection." (PMID 28114324, 2017). "Antigen specific CD4+ and CD8+ T cells are key components of the immune response developed by chronic patients infected with Trypanosoma cruzi, the causative agent of human Chagas disease." (PMID 28552984, 2017). "Among patients with Chagas disease, mean levels of CD4+ T-cell counts were significantly lower in patients with reactivation (131 cells, 95% CI: -56.54–318.54) compared to patients without reactivation (322.46 cells, 95% CI: 229.45–415.47) (t-test with unequal variances: p = 0.046)." (PMID 26919324, 2016). "CCC patients show an increased number of CD4+ and CD8+ IFN-γ-producing T cells in the peripheral blood, with reduced numbers of IL-10-producing CD4+CD25+ regulatory T cells and CD4+CD25+ FoxP3+ regulatory T cells as compared with patients in the ASY form of Chagas disease." (PMID 25210230, 2014). "T cell phenotype of total CD4+ T cells in children in the early stages of Chagas disease." (PMID 24349591, 2013). "Because we found that CD4+CD25+FOXP3+ T cells induced by immunization with rSSP4 promoted the development of Chagas disease, we wanted to see whether these regulatory T cells were antigen specific." (PMID 23509755, 2013). "However, the same authors reported later in a study that patients with the indeterminate form of Chagas' disease exhibited a higher frequency of CD4+CD25high T cell expressing Foxp3 and IL-10 as compared to those individuals with cardiomyopathy." (PMID 22545173, 2012). "In an attempt to better characterize these cells in Chagas' disease, we investigated whether CD25High CD4+ Treg in the peripheral blood of chagasic patients are IL-10 producers." (PMID 21655351, 2011). "Moreover, CD4+ T cells producing IL-2 are also impaired in Chagas disease patients further compromising the T cell function in these patients." (PMID 18846233, 2008). "The significance of the response of CD4+ T cells from Chagas patients that display DERAA to MBP is unclear, but it is tempting to hypothesize that this response might be associated with auto-reactivity in Chagas disease." (PMID 40391216, 2025). "Altogether, these findings suggest a potential role of cytotoxic CD4+ T cells in chronic cardiomyopathy in Chagas disease, which may be inducing cell death of T. cruzi infected cardiomyocytes and endothelial cells, and producing cytokines that help effector functions." (PMID 36447264, 2022). "Finally, B1 patients displayed a unique signature of CD4+ T cell populations during Chagas disease." (PMID 36447264, 2022). "These and other studies conclude that while pro-inflammatory cytokine secreting CD4+T and CD8+T cells and cytotoxic T lymphocytes are essential for protection from infection, the persistence of these cells is detrimental and associated with tissue pathology and tissue damage in Chagas disease." (PMID 34497271, 2021). "On the other hand, the activation of T CD4+ lymphocytes may result in a functional differentiation into Th1, Th2, Th17, or Treg effector cells that differ in terms of their cytokine secretion and trigger distinct immune responses in Chagas disease." (PMID 30405039, 2018). "In Chagas disease, given the size and complexity of the Trypanosoma cruzi proteome and its interaction with the host’s immune system, the fine specificity of T cells has not been extensively studied yet, and this is particularly true for the CD4+ T cell compartment." (PMID 28552984, 2017).
Chagas disease (continued). "Thus, it is likely that CD25High CD4+ T cells use different mechanisms to regulate the immune response during Chagas' disease and that the host-parasite interactions may be influenced by the ratio of regulatory/effectors T cells." (PMID 21655351, 2011). "CD4+CD8+ peripheral T cells seen in experimental Chagas disease exhibited higher amounts of ECM receptors including the integrins VLA-4, VLA-5, and VLA-6, indicating that an abnormal ECM-mediated interaction could be favoring the release of immature thymocytes from the organ." (PMID 16846255, 2006). "Additionally, the presence of perforin-expressing CD4+ cytotoxic T-cells has shown an inverse relationship with LVEF, while an increase in Foxp3+high CD25+high CD4+ T-cells and IL-17 expression has been associated with a positive LVEF and improved cardiac function in human Chagas disease." (PMID 40391216, 2025). "Taken together, our results showed that T. cruzi infection triggers changes in CD4+ T and B cell compartments that are more pronounced in the mild CCC clinical form, suggesting an orchestrated cellular communication during Chagas disease." (PMID 38726014, 2024). "Are increased Frequency of Macrophage-like and Natural Killer (NK) Cells, Together with High Levels of NKT and CD4+CD25high T Cells Balancing Activated CD8+ T Cells, the Key to Control Chagas’ Disease Morbidity?" (PMID 37377258, 2023). "Although the expression of these co-stimulating molecules is essential for the activation or inhibition of lymphocytes, few studies to date have demonstrated the capacity of these receptors to activate CD4+ and CD8+ T lymphocytes in Chagas disease." (PMID 35665256, 2022). "Increased responses were observed in patients with Chagas disease, with the B1 group displaying the higher proportion of responders and the higher frequencies of IFN-γ+ activated CD4+ T cells, mainly among TEM." (PMID 36447264, 2022). "Children with acute asymptomatic Chagas disease presented a lower frequency of CD4+ T cells expressing Vβ5 TCR and normal distribution of the Vβ2, 3.1, 8, and 17-expresing CD4+ T cells." (PMID 36107855, 2022). "This is also in agreement with the higher frequencies of polyfunctional Th1-biased CD4+ and CD8+ T cells specific for T. cruzi observed in subjects with milder forms of chronic Chagas disease than in those with more severe forms." (PMID 34061845, 2021). "The expression of CCR5 by T-cells has been recently addressed by Roffe and colleagues showing that the percentage of effector and effector memory CCR5+ T-cells, both CD4+ and CD8+, were increased in patients with cardiac Chagas disease." (PMID 34336723, 2021). "A similar effect of anti-parasitic treatment on CD8+ T cells from patients in the indeterminate form of Chagas disease and on HIV-specific CD4+ T cells after ART treatment has also been reported." (PMID 33539379, 2021). "The expression of the IL-27R components, WSX-1 and CD130, was evaluated in CD4+ and CD8+ antigen-experienced (CD45RA—) T cells of subjects with different clinical forms of Chagas disease." (PMID 34061845, 2021). "In the case of a Chagas disease vaccine, the ensemble must include CD8+ and CD4+ T cell epitopes as well as B cell epitopes, and thus their positioning and ordering within the construct will have to be carefully studied." (PMID 31824493, 2019). "The exhaustion process in Chagas disease occurs in CD8+ and CD4+ T cells and has been described be more dramatic during more severe stages of disease." (PMID 29750791, 2018). "The inflammatory process occurring in Chagas’ disease mainly consists of CD8 T lymphocytes, CD4 T lymphocytes and macrophages." (PMID 27138039, 2016). "The composition of the inflammatory infiltrate in the digestive forms of Chagas disease includes macrophages, mast cells, eosinophils, CD4+ and CD8+ T cells, B cell and NK lymphocytes, with the CD4+ T cells being the most abundant compared to CD8+ T cells." (PMID 26599761, 2015).